PDX1 (pancreatic and duodenal homeobox 1)
Diseases named in the same sentence as PDX1 in open-access papers (continued):
Sharing a sentence is not in itself a finding about the gene and the disease.
tumor (continued). "Here, the xenograft tumors at necropsy were fixed, paraffin-embedded, and stained with antibodies for pancreatic cell differentiation marker PDX-1, proliferation marker Ki67, and the TUNEL assay to measure apoptotic cells in the tumor." (PMID 35892853, 2022). "We identified cohort-specific DNA methylation markers in the CpG islands of PDX1, EN2, and MSX1 and validated tumor-specific hypermethylation levels of these three genes via optimized qMSP methods with highly sensitive primer sets." (PMID 35169223, 2022). "PDX1 had lower expression and hypermethylation in ATRX/DAXX/MEN1 mutant tumours (T2 and T3) than wild-type tumours (T1)." (PMID 33536587, 2021). "In PDX1, T-DM1 treatment, which reduced tumor growth, resulted in a significant decrease in the number of cluster 2 cells, characterized by high VEGFA expression (P = 3.69 × 108)." (PMID 33886505, 2021). "Mice were orthotopically transplanted with syngeneic 7940B PDAC cells derived from a primary spontaneous PDAC tumor arising in the body of the pancreas (C57BL/6) of a male transgenic KrasLSL-G12D/+, Trp53LSL-R172H/+, Pdx1-Cre (KPC) mouse." (PMID 33348809, 2020). "Immunohistochemical and immunofluorescent evaluation was conducted to characterize organoid expression of tumor markers Maspin, Muc5ac and CRR9, pancreatic marker PDX1 and gastroenteropancreatic and hepatobiliary epithelial marker CK19." (PMID 29587663, 2018). "To investigate the therapeutic impact of BET inhibition by BAY 1238097 in PDAC, we treated tumor-bearing 8 week-old LSL-KrasG12D;Pdx1-Cre;p53ER/ER mice." (PMID 29721157, 2018). "Human serrated morphology CRCs and mouse Cdx2−/− BrafV600E-mutant tumor epithelium aberrantly expressed a number of gastric epithelial markers, including ANXA10, MUC5AC, and PDX1." (PMID 28072391, 2017). "The biodistribution study demonstrated excellent tumor-targeting efficacy and specificity of PRR antibdoy in Pdx1; KrasG12D mouse model." (PMID 28874965, 2016). "To further analyze the role of ARC on β-cell tumor load, we assessed the effects of ARC deletion on β-cell proliferation and apoptosis in Pdx1-Cre; Men1 f/f mice." (PMID 26709830, 2015). "Thus, it is reasonable to speculate that a combined SSTR5-based tumor therapeutic approach including both somatostatin analog and other inhibiting technology of PDX-1 [for example, RNA interference control of PDX-1] would help improve the traditional treatment with somatostatin analogs." (PMID 25009500, 2014).
tumor (continued). "Other than the differences in median survival, the p16−/−; LSL- KrasG12D; Pdx1-Cre and p16flox/flox; LSL- KrasG12D; Pdx1-Cre mice were very similar in their tumor development and metastasis patterns." (PMID 22113502, 2011). "Disruption of the axis through SPHK1 knockdown in CAFs, genetic perturbation of MALL or SDC4 in cancer cells, or adeno-associated virus-mediated SPHK1 or SDC4 knockdown in KPC (KrasLSL-G12D/+; Trp53LSL-R172H/+; Pdx1-Cre) mice significantly reduces PNI and tumor burden." (PMID 42017444, 2026). "Inhibition of MEK1/2 and PI4KB phosphorylation on S256 and T263 in combination effectively suppressed autophagy and inhibited the proliferation of RAS-mutant tumor cell lines, and tumor growth in xenograft and LSL-KrasG12D, p53F/F, Pdx1-Cre mice (KPC) pancreatic cancer models." (PMID 40055523, 2025). "The regulators in C1 LYZ+ tumor cells were mainly FOXA2, PDX1, GATA6, and PPARG." (PMID 40230840, 2025). "Two significant pathways, hsa04080, Neuroactive ligand-receptor interaction, and hsa04950, Maturity onset diabetes of the young (MODoY; with transcription factors FOXA3, NKX6-1, MAFA, PAX6, PDX1), were identified for the genes expressed more highly in the high-CCNE1 tumours." (PMID 38612869, 2024). "To evaluate the anti-tumour activity of RMC-7977 in clinically predictive models of human PDAC, we first performed an interventional survival study in tumour-bearing KrasLSL.G12D/+;Trp53LSL.R172H/+;Pdx1-cretg/+ (KPC) mice." (PMID 38588697, 2024). "To further confirm the tumor suppressive role and rule out any confounding effect of Cas9 endonuclease expression, we generated conditional Usp15fl/fl; KRasG12D; Pdx1-Cre." (PMID 38902237, 2024). "PDX1 (KRASG13D) and PDO1 were originated from the same tumor." (PMID 35307764, 2022). "By examining the differences in the methylation levels observed in tumors and adjacent healthy tissues via hybrid capture-based targeted bisulfite sequencing, we discovered significantly hypermethylated intragenic CGI regions in PDX1, EN2, and MSX1 in the tumor samples." (PMID 35169223, 2022). "In some cases, such as in the case of the distal stomach, PDX1 is expressed in healthy but not cancerous cells, suggesting its role as a tumor suppressor." (PMID 36272648, 2022). "Furthermore, DNA methylation analysis revealed that specific loci in PDX1, EIF2AK4, ASNS, DNAJB2, and FBOX6 were hypomethylated in tumor samples." (PMID 35884393, 2022). "PDX1 resistance to pertuzumab might be explained by the high activity of ER pathways and WNT and Hedgehog signaling in the untreated tumor." (PMID 33886505, 2021).
tumor (continued). "The most recent evidence suggests a possible modulation of the oncogenic/tumor-suppressive properties of PDX1 by non-receptor tyrosine kinase BLK activity." (PMID 34503200, 2021). "In our cohort, the PDX1 gene presented hypermethylated CpG sites in the tumours in subgroups T2 and T3 (mutant ATRX/DAXX/MEN1) compared to tumours in the subgroup T1, which are mainly wild-type for those genes and this subgroup was enriched for functional tumours." (PMID 33536587, 2021). "Some candidate markers, such as IRX3, PDX1 and SCN2A, have not been found to be associated with tumours." (PMID 32649035, 2020). "In the non‐metastatic tumors 12 out of 15 had ARX expression of which 2 were double positive, while 2 tumors had sole PDX1 expression and 1 tumor had no ARX or PDX1 expression (double negative)." (PMID 31846235, 2020). "The PDX-1 tumor growth rate was significantly lowered by KYA1797K treatment (p < 0.01), and the reduction in β-catenin, pan-RAS, and EGFR expression levels in tumor tissues was confirmed." (PMID 32457491, 2020). "Overall, using a representative surgical specimen tumor block as reference standard, 85% of the cytology cases (11/13 correct) were accurate in determining tumor transcription factor subtype (ARX+/PDX1−, ARX−/PDX1+, ARX+/PDX1+, ARX−/PDX1−)." (PMID 31846235, 2020). "Inhibition of RIP1 using Nec-1a in a Kras mutant PDAC model (KPP; LSL-KrasG12D/+; p16/p19fl/fl; Pdx1-cre) after tumors were established had no impact on overall survival or tumor growth." (PMID 31101885, 2020). "Of the intermediate-WT tumours for which IHC data were available (n = 6), two were positive for PDX1, two for ARX and two were negative for both TFs." (PMID 33288854, 2020). "Opposite to the oncogenic role of SOX9 in pancreas carcinogenesis studies in tissues corresponding to later stages of tumor development have found downregulation of SOX9 and other master regulators of embryonic development such as GATA4, PDX1, PTF1a, and HNF1b." (PMID 31057614, 2019). "In the first pathway, PDX1 could upregulate target gene JAM3 to promote the cell immune response and inhibit tumor cell growth." (PMID 31126066, 2019). "Studies on samples from pediatric patients with SPT showed that PDX1 and SOX9 were both expressed in the cytoplasm of SPT cells, supporting the hypothesis that tumor cells originate from pancreatic stem cells persisting after the embryonic period." (PMID 31057614, 2019). "We did not observe tumor formation in Pdx1-Cre;HIF2dPA mice but our analysis was limited to relatively young mice (two-month-old mice)." (PMID 30209343, 2018). "A significant reduction in tumor size was noted in the BGJ398-treated mice compared with vehicle-treated mice in the YAP-positive PDX1 but not the YAP-negative PDX2 animals." (PMID 26826125, 2016). "We followed the transgenic zebrafish for more than one year without observing any evidence of tumor foci or PanIn-like lesions; as opposite to Pdx1-Shh mice that developed metaplastic duct and PanIn-like lesions with over-expressed Ptc1 and Smo." (PMID 22164219, 2011). "Lastly, the tamoxifen induction regimen by itself had no obvious effect on any aspect of RT2 tumorigenesis examined, including tumor invasion, when tamoxifen was applied to RT2 mice that lacked the Pdx1-CreER and DspFlox alleles." (PMID 20862307, 2010). "A minority of intermediate tumours (4/44, 9%) were negative for both PDX1 and ARX." (PMID 33288854, 2020).
tumor (continued). "Because the 395 CRCs were represented as very limited tumor regions in the tissue microarray format, we could not reliably assess relationships of PDX1, CDX2 and ANXA10 staining in these CRCs relative to serrated morphology features." (PMID 28072391, 2017). "Similar histological progression pattern from precancerous lesions to invasive cancer and metastasis was also observed in the p16flox/flox; LSL- KrasG12D; Pdx1-Cre mice, again demonstrating that p16 inactivation promotes progression but does not alter tumor initiation and histology." (PMID 22113502, 2011). "Our study reports a previously unrecognized epidermal expression of PDX1 and adds further evidence for a pivotal role of Notch1 but not Notch2 as a tumor suppressor in the skin, which may be particularly interesting in the light of new therapeutic approaches targeting single Notch receptors." (PMID 21042537, 2010). "In G2, CD56, CgA, NSE, vimentin and Ki-67 were higher in tumour tissue compared to those in non-tumour, and levels of CD44, CD45, CK7, DAXX, synaptophysin and PDX1 were lower in tumour tissue relative to those in non-tumour tissue." (PMID 36362433, 2022). "In contrast to previous reports using high levels of MYC expression driven by Pdx1-Cre;CAGtTA;TetO-Myc32, two copies of ROSA-driven Myc expressed in the pancreas (ROSAMyc/Myc;Pdx-Cre) alone did not induce tumor formation or affect overall mouse survival." (PMID 29170413, 2017). "No significant changes were observed in the number of tumors that developed nor in the collective tumor burden when comparing RT2+; Pdx1-CreER+; DspFlox/Flox mice and littermate controls." (PMID 20862307, 2010). "β-cell hyperplasia was also induced in Pdx1-tTA; tet-o-PyMT-IRES-Luc bitransgenic mice, and the insulin-expressing β-cell hyperplasia does not further progress to form frank neoplasms even after 1 year of oncogene activation and in Ink4a/Arf-null and Arf-null backgrounds." (PMID 19812721, 2009).
cancer (59 papers, 2011 to 2026). A tumor composed of atypical neoplastic, often pleomorphic cells that invade other tissues. "As established previously, genomic or posttranslational dysregulation of PDX1 is linked to cancer and diabetic phenotypes." (PMID 36272648, 2022). "Histologically, ING5 abrogation in gastric stem-like and pdx1-positive cells causes gastric dysplasia and cancer, and conditional ING5 knockout in pdx1-positive and gastric chief cells increases MNU-induced gastric carcinogenesis." (PMID 36425530, 2022). "To determine the possible causes of reduced cancer cell migration during ectopic expression of PDX1, we analyzed changes in the expression of genes related to cell motility." (PMID 34503200, 2021). "We found that KC-OSKM mice given Dox for 1–2 weeks often developed undifferentiated cancers in the stomach, which is consistent with the observation that Cre-LoxP recombination also occurs in the pyloric glands of the stomach with Pdx1-ires-Cre allele." (PMID 29802314, 2018). "However, PDX1 expression may be linked to the changing stages during cancer development and progression." (PMID 32066753, 2020). "Human pluripotent stem cell antibody array analysis of 15 stem cell markers expression indicated that Coala cancer cell line express high levels of E-Cadherin, Fox-A2 and PDX-1 and moderate levels of Snail transcription factor." (PMID 40758205, 2025). "The loss of IPF1/PDX1 function can lead to abnormal cell growth and decreased differentiation of pancreatic cells, creating an environment conducive to cancer development." (PMID 39239563, 2024). "Droplet RNAseq analysis demonstrates that these ductal clusters express embryonic multipotent progenitor cell markers Sox9, Pdx1, and Nkx6-1, and genes involved in actin cytoskeleton regulation, inflammation responses, organ development, and cancer." (PMID 38206366, 2024). "By crossing the Flp-driven KPF with the ExoBow allele, termed KPF-CD63-mCherry, we achieved Flp-mediated expression of CD63-mCherry specifically in cancer cells (Pdx1-Flp; R26CD63-XFP/+; FSF-KrasG12D/+; Trp53Frt/+)." (PMID 38383468, 2024). "We found that spontaneous gastric dysplasia and cancer were more frequently seen in K19-cre+/−;ING5f/f and Pdx1-cre+/−;ING5f/f mice than in the other target KO mice." (PMID 35747809, 2022). "After the exposure to MNU, chemically-induced gastric dysplasia and cancer were more common in K19-cre+/−;ING5f/f and Pdx1-cre+/−;ING5f/f mice than in WT mice." (PMID 35747809, 2022). "Although PDX1 has already been reported as a potential cancer marker in CRC, it is based on the observation of PDX1 expression in cancer cells, and its role has not been studied in detail." (PMID 35169223, 2022). "Our study highlights a potential window for the PDX1 therapeutic application as an antimetastatic agent at the initial stages of cancer development." (PMID 34503200, 2021). "In these models, genetic inactivation of USP9X (either by insertional mutagenesis or Pdx1-Cre mediated deletion) was found to enhance oncogenic KrasG12D in accelerating tumourogenesis and cancer progression." (PMID 34112167, 2021). "In summary, the ectopic expression of PDX1 reduces the migration potential of cancer cells at early stages, particularly by increasing the adhesive properties of cells and reducing the sensitivity of cells to TGFβ1-induced EMT." (PMID 34503200, 2021). "According to our observations, PDX1 ectopic expression of PDX1 reduced the migration potential of cancer cells, in particular, by increasing the adhesive properties of cells and reducing the sensitivity of cells to TGFβ1-induced EMT." (PMID 34503200, 2021).